PTPRF (protein tyrosine phosphatase receptor type F)
Description:
Possible cell adhesion receptor. It possesses an intrinsic protein tyrosine phosphatase activity (PTPase) and dephosphorylates EPHA2 regulating its activity. The first PTPase domain has enzymatic activity, while the second one seems to affect the substrate specificity of the first one.
Synonyms: LAR; BNAH2
Tractability: Small molecule: a structure with a bound ligand is known; a high-quality ligand is known; it belongs to a druggable protein family. Antibody: its Gene Ontology location is reachable by antibodies, with high confidence; UniProt predicts a signal peptide or a membrane-spanning region. PROTAC: ubiquitination databases record sites on it; its protein half-life has been measured; a small molecule that binds it is known.
Target class: Membrane receptor
Gene: Protein-coding gene on chromosome 1 (43,525,086 to 43,626,579, forward strand). Ensembl gene ENSG00000142949.
Subcellular location: Membrane
Subcellular location (Human Protein Atlas): Golgi apparatus
Pathways (Reactome):
Neuronal System: Receptor-type tyrosine-protein phosphatases; Synaptic adhesion-like molecules
Signal Transduction: Insulin receptor recycling
Gene Ontology:
Molecular function: cell adhesion molecule binding; phosphoprotein phosphatase activity; protein binding; protein tyrosine phosphatase activity; transmembrane receptor protein tyrosine phosphatase activity; chondroitin sulfate proteoglycan binding; protein-containing complex binding
Biological process: cell migration; negative regulation of receptor binding; peptidyl-tyrosine dephosphorylation; synaptic membrane adhesion; cell adhesion; cell surface receptor protein tyrosine phosphatase signaling pathway; nervous system development; signal transduction
Cellular component: extracellular exosome; plasma membrane; membrane; neuron projection; neuronal cell body
Genetic constraint (gnomAD): Loss-of-function variants: 56 observed, 201.11 expected, observed/expected ratio (o/e) 0.28, 90% interval 0.22 to 0.35. The upper end of that interval is the gene's LOEUF score, 0.35, which puts it in group 1 of 6, group 1 being the genes least tolerant of losing a copy. Missense variants: 2,117 observed, 2,694.6 expected, observed/expected ratio (o/e) 0.79, 90% interval 0.76 to 0.81. Synonymous variants: 1,079 observed, 1,094.9 expected, observed/expected ratio (o/e) 0.99, 90% interval 0.94 to 1.04.
Homologues: Orthologues: chimpanzee PTPRF (99% identical), macaque PTPRF (99% identical), guinea pig PTPRF (96% identical), rabbit PTPRF (96% identical), pig PTPRF (96% identical), mouse Ptprf (95% identical), rat Ptprf (95% identical), tropical clawed frog ptprf (81% identical), zebrafish ptprfb (77% identical), zebrafish ptprfa (76% identical), dog PTPRF (57% identical). Paralogues in human: PTPRD (69% identical), PTPRS (68% identical), PTPRM (23% identical), PTPRZ1 (23% identical), PTPRK (22% identical), PTPRT (22% identical), PTPRU (21% identical), PTPRG (20% identical), PTPRA (19% identical), PTPRB (17% identical), PTPRE (17% identical), PTPRC (16% identical), and 23 more.
Diseases named in the same sentence as PTPRF in open-access papers:
PTPRF is named in the same sentence as 75 diseases in open-access papers, as found by Europe PMC text mining. Sharing a sentence is not in itself a finding about the gene and the disease. The quoted sentences say what the papers report.
breast carcinoma (12 papers, 2009 to 2022). "In humans, PTPRF is recognized as a tumor suppressor gene; somatic mutations were identified in 9% of breast cancers, and some other malignancies showed significantly increased PTPRF expression." (PMID 21453473, 2011). "High expression of PTPRF has also been reported to reduce cell invasion, migration, and advanced metastasis potential in breast cancer." (PMID 36033512, 2022). "It has been found that high expression of PTPRF is related to the recurrence and metastasis of breast cancer and urothelial carcinoma of the bladder, while knockdown of PTPRF decreases cancer cell invasion and migration." (PMID 34229299, 2021). "Expression levels of BDNF and BDNF-correlated genes CCND2, DUSP6, EGR1, KLF10 and PTPRF are altered in breast cancer." (PMID 19737418, 2009). "Moreover, inhibition of RICTOR or PTPRF was expected to prolong lifespan of breast cancer patients according to patient information annotated in microarray data." (PMID 26336805, 2015). "Although, somatic mutations in the PTPRF gene have been found in many malignancies including breast cancer, its germline mutations have not been identified to cause any known human diseases." (PMID 21453473, 2011). "Computationally, PTPRF, PRKAR2B, MAP4K3, and RICTOR were calculated as highly drug-targetable genes for breast cancer." (PMID 26336805, 2015). "miR-24 targets two regulators (tyrosine-protein phosphatase non-receptor type 9 (PTPN9) and receptor type tyrosine protein phosphatase F (PTPRF)) of EGFR activation, thereby promoting metastasis of breast cancer." (PMID 29455658, 2018).
Insulin resistance (8 papers, 2009 to 2025). Increased resistance towards insulin, that is, diminished effectiveness of insulin in reducing blood glucose levels. "Insulin resistance may lead to coronary artery disease, and in two studies indeed the intronic polymorphism rs2782641 in PTPRF was found to associate with the disease as a recessive trait in type 2 diabetic patients." (PMID 36755664, 2022). "Overexpression studies pointed to a role for LAR in dephosphorylating the insulin receptor and, in line, one report linking a genetic PTPRF promoter variant to obesity and insulin resistance appeared in the literature." (PMID 36755664, 2022). "PTPRF overexpression has been shown to induce insulin resistance in transgenic mice, and insulin receptor tyrosine phosphorylation and kinase activity were found to be increased by the reduction of PTPRF expression." (PMID 23762820, 2013). "In particular, protein tyrosine phosphatase, receptor type, F (PTPRF) may serve as a biomarker linking insulin resistance with insufficient milk supply." (PMID 23861770, 2013). "Specifically, regarding genes related to insulin resistance pathway, we highlight SOCS3, GSK3B, STAT3, PTEN, TRIB3, FOXO1, and PTPRF, along with MAPK8, which plays a role in metabolic stress and inflammation." (PMID 41282288, 2025). "Here, we found genes related to insulin resistance and DM2 (PTPRF and CTLA4 altered in BSCL2mut; IGFBP4 altered in both CGL types)." (PMID 38755198, 2024).
hepatoma (7 papers, 2003 to 2025). "In addition, miR-145-5p expression led to inhibition of the phosphatase PTPRF in biliary tract but not hepatocellular carcinoma cell lines." (PMID 30886199, 2019).
glioma (5 papers, 2018 to 2024). A benign or malignant brain and spinal cord tumor that arises from glial cells (astrocytes, oligodendrocytes, ependymal cells). "An article has already shown that PTPRF contributes to the development of glioma, while a systematic study of how circPTPRF affects GBM progression is still lacking." (PMID 36397164, 2022).
lung carcinoma (4 papers, 2021 to 2024). "Interestingly, some studies regarded PTPRF as the potential predictor for treatment with Erlotinib in lung cancer, indicating the clinical application of PTPRF in cancer therapy." (PMID 36341348, 2022). "While the associations of PTPRF and FASTKD3 with COPD are not as clear, links between these two genes and lung cancer prognosis suggest some degree of activity within the lung through their roles in apoptosis, cell growth and differentiation, and oncogenesis." (PMID 37143066, 2023).
melanoma (4 papers, 2013 to 2023). A malignant, usually aggressive tumor composed of atypical, neoplastic melanocytes. "PTPRF (LRRC4B receptor) is reported as a melanoma biomarker and confirmed by another study using Genome-wide microarray analysis." (PMID 36777724, 2023). "Curiously, one study reported the opposite finding, showing that PTPRF was over-expressed in metastatic and primary melanoma cells in vitro and in situ compared to melanocytes." (PMID 35606887, 2022). "Low level PTPRF expression in normal epidermal contrasted with higher expression (both cytoplasmic and nuclear) in melanoma cells." (PMID 23638386, 2013). "While SHC4 has been reported previously to be associated to melanoma, this is the first time CXCL13, COL11A1, and PTPRF have been associated with melanoma on experimental validation." (PMID 23638386, 2013). "Third, we validated the expression of MAPK-associated members (COL11A1, CXCL13, PTPRF, SHC4) of the 12-gene biomarkers in a comparative analysis of normal melanocytes and melanoma cells in vitro and in primary versus metastatic melanoma biopsy tissue in situ." (PMID 23638386, 2013). "Then, we identified 9 LR pairs (“BMP6- > HJV” 、"CCL8- > ACKR4” 、"DLL3- > NOTCH3"、"DSC3- > DSG3"、"GHRH- > GHRHR” 、"LRRC4B- > PTPRF"、"SEMA4D- > PLXNB1"、"SFRP1- > FZD6"、"UCN- > CRHR1′′) as key LR pairs in melanoma prognosis through Lasso Cox regression and Multiple Stepwise Regression." (PMID 36777724, 2023). "PTPRF is overexpressed in primary melanoma and metastasis of malignant melanoma." (PMID 30641895, 2019). "Note that COL11A1, CXCL13, and PTPRF have not previously been reported to be associated with melanoma experimentally." (PMID 23638386, 2013). "COL11A1, CXCL13, PTPRF, and SHC4 were found to be over-expressed in two human melanoma cell lines (i.e., FM55 and FM94) compared to normal human epidermal melanocytes in vitro." (PMID 23638386, 2013). "The over-expression of COL11A1, CXCL13, PTPRF and SHC4 in our melanoma cell lines and primary and metastatic tissue, and their potential association with MAPK pathways suggests they could be specific biomarkers for melanoma and so potential therapeutic targets." (PMID 23638386, 2013). "The fact that PTPRF is not only overexpressed in metastasis but also in primary melanoma suggests that there is no relevant trend in expression during tumor progression." (PMID 30641895, 2019). "The over-expression of COL11A1, CXCL13, PTPRF, and SHC4 in melanoma cells in vitro and in situ may reflect the observed over-expression of the associated genes in our microarray meta-analysis results." (PMID 23638386, 2013).
schizophrenia (4 papers, 2018 to 2025). A major psychotic disorder characterized by abnormalities in the perception or expression of reality. "PTPRF, the gene encoding human LAR, has been associated with ADHD and schizophrenia in genome-wide association studies, but the molecular consequences of PTPRF perturbations have remained largely unstudied." (PMID 40502755, 2025). "As expected, there was also limited concordance between schizophrenia and ADHD (r = 0.0705), particularly for downregulated genes, and six (MAD1L1, KDM4A, IPO13, ATP6V0B, DPH2, PTPRF) of the nine placental genes associated with ADHD were also significantly associated with schizophrenia." (PMID 37188697, 2023).
prostate carcinoma (3 papers, 2021 to 2025). A carcinoma that arises from epithelial cells of the prostate gland. "Result showed that COL3A1 and SDC2 were found to be the highest risk factors of prostate cancer, followed by RAC1 and PTPRF." (PMID 34229299, 2021). "However, PTPRF ectodomain was upregulated in a prostate cancer mouse model, as well as in metastatic breast cancer suggesting that altered expression of PTPRF/LAR is tumor type dependent." (PMID 34654889, 2021). "In prostate cancer, a novel risk model comprising five genes, namely poly(rC) binding protein 1 (PCBP1), PABPN1, protein tyrosine phosphatase receptor type F (PTPRF), differentiation antagonizing non-protein-coding RNA (DANCR), and MYC, was established for predicting progression-free survival (PFS)." (PMID 40607380, 2025).
amyotrophic lateral sclerosis (2 papers, 2019 to 2021). Amyotrophic lateral sclerosis (ALS) is a neurodegenerative disease characterized by progressive muscular paralysis reflecting degeneration of motor neurons in the primary motor cortex, corticospinal tracts, brainstem and spinal cord. "Previous studies have shown that the homologous gene of PTPRF, protein tyrosine phosphatase sigma, a receptor of chondroitin sulfate proteoglycans, is highly expressed in abnormal astrocytes in amyotrophic lateral sclerosis and inhibits their regeneration." (PMID 31611906, 2019).
breast tumor (2 papers, 2015 to 2021). "Five genes (SEMA3F, BLVRB, PTPRF, MARCKS, and CQQ6) are up regulated both in HER2 positive cell lines and in high HER2 expressing primary breast tumor tissues." (PMID 25428913, 2015).
colitis (2 papers, 2016 to 2025). Inflammation of the colon. "Loss of PTPRF in mice has been shown to cause hyperactivation of plasmacytoid dendritic immune cells and mild colitis." (PMID 40000109, 2025). "Thirty-seven (37 = 58.7%) of these DMRs associated with genes, but only 6 (16.2%) of those have been implicated in either colitis (PTPRF, ELTD1, and GDNF) or CRC (PTPRF, ELTD1, PDX1, CCK, and AGPAT1)." (PMID 27006956, 2016).
colorectal cancer (2 papers, 2016 to 2019). A primary or metastatic malignant neoplasm that affects the colon or rectum. "Previous studies on the mutational analysis of the tyrosine phosphatase gene superfamily in human cancers identified 83 somatic mutations in six PTPs (PTPRF, PTPRG, PTPRT, PTPN3, PTPN13, PTPN14), affecting 26% of colorectal cancers and a smaller fraction of lung, breast and gastric cancers." (PMID 27833130, 2016).
diabetes (2 papers, 2010 to 2013). "The R2A PTP subfamily includes PTPRF, PTPR sigma (PTPRS), and PTPR delta (PTPRD), and it has been implicated in neural development, cancer, and diabetes." (PMID 23762820, 2013).
gastric cancer (2 papers, 2022 to 2024). A primary or metastatic malignant neoplasm involving the stomach. "Downregulation of Protein tyrosine phosphatase, receptor type F (PTPRF) expression has been reported in advanced tumour stages and in poor OS prognosis in gastric cancer." (PMID 36033512, 2022).
leukemia (2 papers, 2021 to 2024). A malignant (clonal) hematologic disorder, involving hematopoietic stem cells and characterized by the presence of primitive or atypical myeloid or lymphoid cells in the bone marrow and the blood. "Initially identified though its role in leukemia research, PTPRF regulates cell proliferation and differentiation by acting on downstream substrates, akin to the function of many other phosphatases." (PMID 39026678, 2024).
liver cancer (2 papers, 2021). An epithelial or non-epithelial malignant neoplasm that arises from the liver. "PTPRF/LAR suppresses liver cancer tumorigenesis, and reduced expression of PTPRF/LAR leads to development of tumors." (PMID 34654889, 2021).
viral infection (2 papers, 2012 to 2017). "When cells were treated with 20 μM MG132, EPHA2 and ALCAM the protein levels in Ad5-infected cells remained comparable to those of mock-infected cells, whereas, surprisingly, PTPRF levels were decreased in MG132-treated cells, even without viral infection." (PMID 28631589, 2017).
alopecia areata (1 paper, 2023). Loss of scalp and body hair involving microscopically inflammatory patchy areas. "The regulatory role of miR-199a-3p in the PTPRF/β-catenin axis was confirmed, further demonstrating the link between alopecia areata and the Wnt-signaling pathway." (PMID 38139460, 2023). "To validate the hypothesis regarding the involvement of miR-199a-3p in mediating the regulation of the PTPRF/β-catenin axis in alopecia areata, we established a novel mouse model of alopecia areata." (PMID 38139460, 2023).
biliary tract cancer (1 paper, 2019). "MiR-145-5p also reduced PTPRF at the protein level in biliary tract cancer cell lines." (PMID 30886199, 2019). "Although we were not able to show direct effects of miR-145-5p on PTPRF or PTPRS, our results suggest an important functional role of miR-145-5p in biliary tract cancer and clearly demonstrate the activation of STAT1 signaling by miR-145-4p." (PMID 30886199, 2019).
Bladder cancer (1 paper, 2014). "We chose five candidate genes (PTPRF, MMP2, VEGFA, CDH1 and CLDN7) that were detected differential expression by Cuffdiff and involved in Bladder cancer pathway, cell adhesion molecules (CAMs) pathway and focal adhesion pathway." (PMID 24622401, 2014).
bladder tumor (1 paper, 2019). "PTPRF has been shown previously to inhibit β-catenin phosphorylation leading to reduced cell migration and inhibition of a rat bladder tumor cell line in a xenograft mouse model." (PMID 30886199, 2019).
Breast hypoplasia (1 paper, 2023). Underdevelopment of the breast. "In MCF7 cells, the most E2-responsive phospho-site was S1294 in protein tyrosine phosphatase receptor type F (PTPRF), a protein known to play a role in congenital breast hypoplasia and murine mammary gland development." (PMID 37608351, 2023).
colon cancer (1 paper, 2019). "Another study in the human embryonic kidney cells HEK293 demonstrated that PTPRF dephosphorylates the death-associated protein kinase (DAPK) which has been suggested to be involved in colon cancer progression." (PMID 30886199, 2019).
demyelinating disease (1 paper, 2019). A broad group of disorders that affect the myelin sheaths that cover the neurons. "However, the specific mechanism of PTPRF and RAD23B in immune-mediated demyelinating diseases remains to be confirmed." (PMID 31611906, 2019).
Gall Bladder Carcinoma (1 paper, 2022). "Hence, it was concluded that the downregulation of PTPRF (protein tyrosine phosphatase receptor type F), activation of STAT-1, and cell proliferation were noted in gallbladder carcinoma cells in comparison to the nonneoplastic cells." (PMID 35035811, 2022).
gastric tumour (1 paper, 2022). "Conversely, overexpression of PTPRF has been shown to suppress gastric tumour migration and invasion by deactivating ERK1/2 signalling." (PMID 36033512, 2022).
Huntington disease (1 paper, 2021). Huntington disease (HD) is a rare neurodegenerative disorder of the central nervous system characterized by unwanted choreatic movements, behavioral and psychiatric disturbances and dementia. "Decreased expression of PTPRF has been observed in induced pluripotent stem cells (iPSCs) obtained from Huntington’s disease (HD) patients, which could have a role in some pathological features of this diseases, such as neural dysfunction and cell death (The HD iPSC Consortium, 2012)." (PMID 34966732, 2021).
lung adenocarcinoma (1 paper, 2023). A carcinoma that arises from the lung and is characterized by the presence of malignant glandular epithelial cells. "FSCN1-induced PTPRF-dependent tumor microenvironment inflammatory reprogramming promotes lung adenocarcinoma progression via regulating macrophagic glycolysis." (PMID 37604869, 2023).
mastitis (1 paper, 2025). Inflammation of breast tissue during lactation or postpartum due to an obstructed duct or infection. "The significant expression changes observed for PTPRF in the KD and OE groups indicate that miR-223 may regulate mastitis resistance by modulating the activity of this gene." (PMID 40033327, 2025). "The identification of DEGs and potential target genes, particularly PTPRF, DCTN1, PLEC, MYOF, and DPP9, underscores the critical role of miR-223 in modulating mastitis-related traits in dairy cattle." (PMID 40033327, 2025). "By regulating critical genes such as PTPRF, DCTN1, and DPP9, miR-223 emerges as a key molecular modulator that balances cellular processes, contributing to mastitis resistance and production traits like milk yield and fat content." (PMID 40033327, 2025).
meningioma (1 paper, 2007). A generally slow growing tumor attached to the dura mater. "In addition, we found induction of IGFBP3, CENPF, CKS2 and reduction of LTBP2, PTPRF in high-grade meningiomas as previously reported." (PMID 17937814, 2007).
metastatic melanoma (1 paper, 2013). A melanoma that has spread from its primary site to another anatomic site. "By contrast, PTPRF was intensely expressed in the majority of tumor cells of both primary and metastatic melanoma cells." (PMID 23638386, 2013).